LEP (leptin)
Diseases named in the same sentence as LEP in open-access papers (continued):
Sharing a sentence is not in itself a finding about the gene and the disease.
tumor (continued). "Moreover, leptin has been shown to regulate the metabolic fitness of CD8+ T cells and control their effector function in the tumour microenvironment and the responses to anti-PD-1 therapies." (PMID 34031386, 2021). "Leptin produced by obASCs mediated EMT in vitro and promoted tumor metastasis in vivo." (PMID 34350120, 2021). "For instance, leptin has increased proliferation of colon cancer cells in vitro however, it failed to support the tumor growth in vivo." (PMID 34588926, 2021). "Leptin, another adipokine, was also found to shape the TME and contribute to tumor development." (PMID 33391518, 2021). "Regarding potential mechanisms, leptin can activate the JAK2/STAT3, PI3K/Akt/mTOR, and extracellular regulated protein kinase (ERK) pathways by binding to its own receptors expressed in tumor cells and stromal components, including immune cells, endothelial cells and tumor-associated fibroblasts." (PMID 33842335, 2021). "Furthermore, to investigate the relationship among BMI and leptin levels and OBR, pSTAT3, CEBPD, and MCL1 expression, patient serum and tumor specimens were evaluated by ELISA and IHC, respectively." (PMID 34156978, 2021). "Increased leptin, IL-8, IL-6, and IL-1β concentrations is reported in MDA-MB-231 and MDA-MB-468 cells after co-cultivation with adipocytes or adipocyte-conditioned medium favouring tumour cell survival and progression." (PMID 34812105, 2021). "In addition, leptin stimulation was found to promote the migration and invasion of cultured HCT-116 cells, tumor growth in the xenograft model and the upregulation of SIRT1." (PMID 33799880, 2021). "The correlation between serum LEP level and both tumor size and tumor grade in patients with HCC was slightly negative correlated." (PMID 33369452, 2020). "Here we show that leptin can also induce VEGFA expression in macrophages, suggesting that adipocyte-derived signals may promote tumorigenesis by influencing the tumor microenvironment, as well as the tumor cells directly." (PMID 32318345, 2020). "In this study, we evaluated whether the leptin/LEPR/KHDRBS1 axis, reported in the cellular model as relevant to tumour progression, could be expressed in bone metastatic tissue in vivo." (PMID 33213024, 2020). "Secondly, the amount of leptin in the gastrocnemius correlated positively with the amount of soluble PECAM and MMP2 in the same tissue as well as with different actors of the tumour oxidative status (total glutathione, glutathione-S-transferase, glutathione reductase, thioredoxin and COX-2)." (PMID 32472095, 2020). "Our team has already demonstrated that MECs express high levels of adiponectin in breast tissue adjacent to tumor samples, an adipokine known to have antiproliferative activities, and to not express leptin, an adipokine with procarcinogenic properties." (PMID 33505957, 2020). "Moreover, the expression levels of LEP, DLX2, CLSTN2, and REG3A were significantly higher in tumor tissues than normal tissues." (PMID 33194689, 2020). "Nude mice xenograft tumor experiments further confirmed that reducing lnc-REG3G-3-1 can inhibit the tumor growth by inducing increased miR-215-3p and decreasing the expression of leptin and SLC2A5 in vivo." (PMID 32903414, 2020). "Adipose tissue secretes leptin, VEGF, IL-1, IL-6, hepatocyte growth factor (HGF) and TNF-α that could induce tumor neoangiogenesis leading to the progression of solid tumors." (PMID 32977765, 2020). "In this way, KHDRBS1 may play a role in amplifying the response of bone metastasis to leptin, which would underscore the relevance of the leptin/LEPR system in tumour progression." (PMID 33213024, 2020). "However, in recent years the role of leptin as an inducer in EMT, as well as in tumor progression, has become very important." (PMID 33334030, 2020). "Although the positivity of leptin has been reported in general, the intensity of leptin positivity has not been shown in tumor subgroups that were considered for the current study." (PMID 30803210, 2019).
tumor (continued). "Leptin and adiponectin had similar dynamics in all subgroups irrespective of tumor localization, the use of nCRT, the surgical technique used or the presence or absence of weight loss." (PMID 31425509, 2019). "Leptin and its receptor were cytoplasmically expressed in tumor cells and were negative in normal astrocytes as observed in other studies." (PMID 30803210, 2019). "However, in vitro studies demonstrated that leptin also induces the epithelial-mesenchymal transition (EMT), cell migration and MMPs are secreted in the tumor microenvironment in breast epithelial cells." (PMID 31671408, 2019). "Additionally, treatment of PC with adiponectin or an adiponectin receptor agonist, AdipoRon, suppressed leptin-induced STAT3 signaling in vitro and reduced tumor growth." (PMID 30004402, 2018). "Our present study indicated that MCP1 contributes to inflamed tumor microenvironment and the increase of chemokines can be detected in prediagnostic blood in lean women, and it may operate with PAI1 and leptin as shown by the composite score analysis." (PMID 29573228, 2018). "Binding of leptin to its receptor activates transcription (JAK/STAT) and Ras/extracellular signal-regulated kinase (ERK1/2) signal transduction pathways, inducing tumor cell proliferation and migration and suppressing apoptosis." (PMID 30379922, 2018). "Moreover, lycopene suppresses tumor cell invasion mediated by leptin as proteomic assays revealed that lycopene exposure significantly decreased expression levels of MMP7 and thereby reduce the tumor cells invasion capacity." (PMID 30487390, 2018). "In our study, after dividing the PTC patients into two groups based on tumor size, we did not observe the differences in serum leptin concentrations." (PMID 30627158, 2018). "The adipocytes from leptin-deficient ob/ob mice showed no enhanced proliferation effect on tumor cells unless exogenous leptin was administrated." (PMID 30013512, 2018). "Given the tumor suppressor and anti-invasive roles of CCN5 in BC, we used molecular techniques to investigate whether leptin has any influence on CCN5 to promote BC progression." (PMID 29370782, 2018). "While there was no proliferation difference between wild-type and leptin- expressing tumor cells in vitro, these cells are controlled in vivo in a CD8+ T cell specific manner." (PMID 30400822, 2018). "The increased level of leptin is reported in salivary gland neoplastic tissues, while ghrelin is expressed in the healthy tissue and is absent in tumours." (PMID 30155477, 2018). "The increased leptin could bind to LepR and activate Jak2/STAT3 signaling in BMSCs, thus forming more BMAs and creating a positive feedback for tumor cells." (PMID 30013512, 2018). "Unlike the pro-tumor effect of leptin, most of the studies demonstrated that adiponectin had anti-tumor effects." (PMID 30013512, 2018). "Mann Whitney U-test performed between 43 weeks old non-operated and operated mice that developed neoplasia showed decreased glucose, C-peptide and leptin levels." (PMID 29662006, 2018). "However, leptin decreases the expression of CCN5 in MCF7 cells, favoring tumor progression by the induction of EMT through a mechanism regulated by the JAK–Akt–STAT pathway." (PMID 30404206, 2018). "WB analyses of pooled tumor lysates showed that PC xenografts derived from leptin treated-tumorspheres had significantly higher levels of Notch4, DLL4, JAG1, survivin, PCNA and Oct-4." (PMID 27999190, 2017). "It is well known that adipocytes contain a variety of tumor promoting factors, even in estrogen-negative cells, like adiponectin, leptin, collagen IV, and hepatocytes growth factor." (PMID 28327169, 2017). "Here, we investigated whether leptin increases PC cell proliferation and Notch expression, and whether a leptin-Notch axis induces PCSC and tumor development in a mouse xenograft model." (PMID 27999190, 2017).
tumor (continued). "In addition to activating anti-tumor cytokines, JC-001 inhibited the expression of pro-tumor cytokines, including leptin, LIX (CXCL5) and SCF, in both the tumor microenvironment and in serum." (PMID 28399860, 2017). "Regardless, it seems that ADIPO and LEP can serve as reliable predictors of the overall tumor growth microenvironment in any individual, regardless of adiposity, making them potential clinical markers of the tumor growth environment." (PMID 28873415, 2017). "We could also show that leptin activates potent oncogenic pathways depending on JAK2/STAT3, AKT and ERK1/2 in the tumor cell line that carried a high-copy amplicon on the locus of the leptin receptor." (PMID 26871287, 2016). "LEP, ADIPOQ, and OXTR manifest lower expression in tumor samples." (PMID 27857161, 2016). "Besides IL-8 which is involved in leptin-induced EMT, this study has found that PKM2 is another critical molecule affecting tumor progression." (PMID 27769315, 2016). "Moreover, leptin-induced STAT3 phosphorylation increased stemness in embryonic and tumor tissues, which was regulated by the feedback actions of pluripotency-associated transcription factors (i.e., NANOG, OCT4, SOX2)." (PMID 27472371, 2016). "This association was positive with adiponectine but negative with leptin, which is in favor of tumor suppression." (PMID 27248826, 2016). "Leptin however upregulates pro-inflammatory and pro-tumor IL-6 yet does not alter anti-inflammatory IL-10 expression." (PMID 25599228, 2015). "After tumor cells were injected and tumors started developing, all mice started losing weight progressively, regardless of their anti-leptin signaling treatment or lack thereof, and they were euthanized four weeks after starting treatments." (PMID 25599228, 2015). "Although leptin was capable of stimulating Panc02 and Panc1 cell proliferation in vitro, leptin does not appear to significantly contribute to the tumor cell proliferation in vivo." (PMID 25919692, 2015). "Leptin has been reported to enhance aromatase activity in MCF-7 cell lines which may enhance estrogen production and induce tumor cell growth." (PMID 25838618, 2015). "The association of irisin levels with the presence of disease and tumor characteristics but not with BMI suggests that this factor is more likely to be related to systemic disease and tumor extent rather than to adiposity, as previously reported for leptin." (PMID 26560078, 2015). "The limitations of this study include its retrospective nature and the lack of tumor biology data such as gene mutation and expression as well as laboratory data regarding serum IGF1, insulin, and adipocyte-derived leptin levels." (PMID 26684001, 2015). "Interestingly, the Akt/PI3K/mTOR cascade mediates signalling from leptin and IL-6, which in our have been shown to be significantly elevated in EDBC patients and positively correlated with tumour stage." (PMID 25338520, 2014). "Indeed, MDAMB-231 cells form more aggressive tumours than MCF-7 cells and secrete higher levels of leptin and VEGF." (PMID 25482303, 2014). "In the benign disease group, there was no significant change in serum leptin levels, possibly due to the fact that these patients were immediately replaced with thyroxine and were euthyroid at the time of leptin measurement." (PMID 24867470, 2014). "The lower expression of leptin as a result of a reduction in white adipose tissue and the reduced leptin expression within the adipose tissue in the NAG-1Tg/Lox mouse provide one mechanism by which NAG-1 may act to alter inflammation and tumor growth." (PMID 23737651, 2013). "Leptin signals also impacted tumor stroma, noncancerous cells including fibroblasts, immune and endothelial cells, ability to produce VEGF." (PMID 24202338, 2013). "Mice lacking the leptin gene (ob−/ob−) have very high levels of white adipose tissue but are devoid of leptin expression and have a lower tumor burden after treatment with AOM." (PMID 23737651, 2013).
tumor (continued). "The aim of the present study was to detect the expression of leptin and OBRs in a group of Chinese mainland PTC patients, and to determine whether their expression correlated with patient and tumor characteristics." (PMID 23425972, 2013). "Adiponectin:leptin ratio is significantly increased in EE non-tumor and tumor-bearing mice compared to SE non-tumor and tumor-bearing mice respectively." (PMID 23272114, 2012). "Non-tumor-bearing EE mice showed a significant increase in adiponectin levels but no change in those of leptin, F2-isoprostanes, PGF2α, IL-6, TNF-α, PAI-1, and MCP-1 levels." (PMID 23272114, 2012). "This phenomenon was also observed, after the addition of DHA (Docosahexaenoic acid), an other derivative of α-linolenic acid, in the presence and absence of leptin in rat glial and pituitary cells tumor." (PMID 21991326, 2011). "The tumor weight, EPC numbers and NOx level in leptin, PBS, 9F8, and IgG group were (3.2 ± 0.6, 1.7 ± 0.3, 1.61 ± 0.2,1.7 ± 0.3 g), (222.66 ± 36.5, 133.33 ± 171, 23.33 ± 18, 132.66 ± 27.26/ml of blood), and (22.47 ± 5.5, 12.30 ± 1.5, 6.26 ± 0.84, 15.75 ± 6.3 μmol/L) respectively." (PMID 21338489, 2011). "The effect of cigarette smoke on NK cell ability to kill K562 tumour cells was assessed in the presence or absence of the adipokines leptin and adiponectin." (PMID 20107494, 2010). "The tumor promoters 12-phorbol-13-myristate-acetate (PMA) and staurosporine or the anti-estrogen tamoxifen, H2O2 producing oxidative stress, leptin, IL-6 or staphylococcal endotoxin B, activin or anisomycin, did not significantly influence CCHCR1 mRNA levels (data not shown)." (PMID 19551138, 2009). "The study results’ discrepancies may be also partially attributed to the cellular and molecular complexity of the tumor microenvironment, considering that the balance between PRAT-derived leptin and adiponectin level may be a key factor that promotes carcinogenesis." (PMID 40227577, 2025). "Based on these findings, the present study investigates the role of leptin within obese AT-derived EVs and its contribution to the malignancy of TNBC, specifically focusing on how metabolic reprogramming underpins aggressive tumor behavior and mitochondrial dynamics." (PMID 40485730, 2025). "Leptin promotes endothelial tube formation and increases vascular permeability by synergising with VEGF and fibroblast growth factor 2 (FGF-2), thereby facilitating tumour vascularisation and the establishment of a permissive vascular–stromal interface for cellular invasion." (PMID 41586225, 2025). "Increasing research indicates that adipokines (such as leptin, resistin, visfatin, etc.)and inflammatory factors (such as IL-1β, IL-6, chemokines, FABP4, etc.)secreted by BMA can also regulate angiogenesis, indirectly facilitating the progression of tumor bone metastasis." (PMID 38571500, 2024). "Previous study analyzed the expression of LEP, long isoform of LEPR and short isoform of LEPR in 322 primary BC tissues and found that the long isoform of LEPR and the short isoform of LEPR were expressed in all tumor tissues and LEP was expressed in 318 samples." (PMID 36941557, 2023). "Moreover, this study also found that the expression of LEP and LEPR were balanced when stratified by patients’ age, menopausal status, tumor size, tumor pathological classification, distant metastasis and the expression of ER and PR, which was consistent with previous study." (PMID 36941557, 2023). "Determination of serum leptin and adiponectin levels may be useful in the diagnosis of PanNENs and could serve as a potential prognostic and predictive biomarker for PanNENs, especially by evaluating their levels with other known NEN tumor markers." (PMID 37444627, 2023). "However, their study was limited to demonstrating changes in autophagy, and did not evaluate the effects of leptin-mediated autophagy on characteristics related to tumor progression." (PMID 36291097, 2022).
tumor (continued). "In double transgenic mice, the microenvironment displays high local levels of leptin under obese conditions, which increases the leptin receptor-mediated pathway, including elevated PI3K, ERK1/2, and STAT3 activation, resulting in the acceleration of tumor progression." (PMID 35563777, 2022). "However, in contrast to obese animals, in which serum leptin is elevated, our tumour-bearing mice were not obese, and we did not detect a significant increase in serum leptin during tumour progression." (PMID 36450983, 2022). "Indeed, administration of exogenous recombinant leptin rescued tumor growth defects and reverses the vascular normalization phenotype in GLSECKO mice, suggesting that leptin is one mechanism through which endothelial glutamine metabolism controls tumor growth." (PMID 36381236, 2022). "Second, serum LEP levels do not show a significant difference between tumor stages." (PMID 34414945, 2021). "The median serum levels of AFP, PIVKA-II, GPC-3, adiponectin and IL-6 were significantly higher in patients with HCC compared to those without tumor (all p < 0.001); only the plasma leptin values were not different between the two groups of patients (p = 0.649)." (PMID 34064999, 2021). "Leptin neither enhanced the growth of the cells nor interfered with AdipoRon, a finding consistent with the absence LepRb; additionally we excluded palmitic acid as a tumour growth-enhancing factor since it promoted Panc02-Luc-ZsGreen cell death." (PMID 33536560, 2021). "However, as in the adrenal NCI–H295 tumor cell line and primary adrenal cells, we did not observe any significant effects of leptin on endocrine pituitary or adrenocortical progenitors." (PMID 33157254, 2021). "In addition, tumor-positive sentinel lymph nodes had enhanced leptin expression as compared to tumor-negative sentinel lymph nodes." (PMID 34068679, 2021). "The gastrocnemius and tumour leptin levels decrease without changes in IAT or plasma levels." (PMID 32472095, 2020). "Research indicates that leptin is produced and secreted from VAT, but the relative contribution of circulating leptin to the local release of leptin from the mammary adipose tissue or to tumor progression is unknown." (PMID 33019728, 2020). "Leptin is not available for tumour growth while physical activity consumes it." (PMID 32472095, 2020). "Yet, most of the evidence points at leptin to be a tumor promoter, to have negative effects on HCC." (PMID 33316927, 2020). "Leptin was strongly correlated with sex, but not with other tumor-related factors." (PMID 33334030, 2020). "HDL-cholesterol, glucose and leptin of rats fed the control diet non-inoculated (C), diet added with xanthan gum non-inoculated (XG), control diet inoculated with Walker 256 tumor cells (TC) and diet added with xanthan gum inoculated with Walker 256 tumor cells (TXG)." (PMID 31211796, 2019). "Plasma leptin levels were not altered significantly by the presence of the tumor or by RT." (PMID 31752313, 2019). "Moreover, the results of other studies have indicated that the expression of the leptin and its receptor in the CRC patients could correlate with the tumor differentiation grade and depth of bowel wall invasion." (PMID 31231490, 2019). "Therefore, under chronic obese conditions a functional crosstalk may exist between LPA, leptin, and PAI-1 in the regulation of arteriolar remodeling of tumor microvasculature to promote de novo tumor arteriogenesis." (PMID 28186980, 2017). "However, at 11 and 13 weeks of age (P = 0.017, 0.0043, respectively, data not shown) and at sacrifice, plasma leptin concentration negatively and significantly correlated with tumor latency (P = 0.0029)." (PMID 27042159, 2016). "Furthermore, the polymorphisms rs7799039 in LEP and rs1137101 in LEPR increased the risk for developing DTC, although they did not appear to correlate with tumour aggressiveness." (PMID 25810718, 2015).